Y_RNA (Y RNA )
Gene: Miscellaneous RNA gene on chromosome 11 (24,455,911 to 24,456,010, forward strand). Ensembl gene ENSG00000207252.
Homologues: Orthologues: chimpanzee Y_RNA (99% identical), macaque Y_RNA (91% identical). Paralogues in human: RNY3 (90% identical), Y_RNA (90% identical), Y_RNA (89% identical), Y_RNA (88% identical), RNY3P14 (87% identical), Y_RNA (87% identical), Y_RNA (86% identical), Y_RNA (85% identical), RNY3P1 (84% identical), RNY3P2 (84% identical), RNY3P9 (84% identical), Y_RNA (84% identical), and 94 more.